EPCAM (epithelial cell adhesion molecule)
Diseases named in the same sentence as EPCAM in open-access papers (continued):
Sharing a sentence is not in itself a finding about the gene and the disease.
tumor (continued). "Anti-EpCAM antibodies can used to identify tumour cells within heterotypic cell populations." (PMID 39376603, 2024). "Commercially available assays are available for the detection of CTCs in CSF, which can detect tumor cells based on cell surface proteins such as an epithelial cell adhesion molecule (EpCAM), which is a transmembrane glycoprotein detected in cells of epithelial origin." (PMID 39200256, 2024). "Combined with our results, EpCAM may promote the formation of tumor colonies by enhancing tumor cell activity in the early stage of tumor formation." (PMID 38187284, 2024). "Furthermore, we sorted EpCAM+ tumor cells from resistant and sensitive PDX tumors and discovered that DAG and TAG predominantly originated from these cells." (PMID 39436710, 2024). "Cell clustering identified two malignant tumor cell populations defined by EpCAM+ epithelial cells." (PMID 38772416, 2024). "We also used SIDR-seq on 14 tumor tissues sorted by surface EpCAM." (PMID 38892065, 2024). "Compared with the common T cell group, EpCAM-CAR-T cells had strong a cytotoxic impact against EpCAM-positive tumour cells, and EpCAM-CAR-T cells could secrete a large amount of TNF-α and INF-γ." (PMID 39107717, 2024). "Based on the intracranial administration, early contact of EpCAM-directed CAR T-cell with EpCAM-transduced LL/2 tumor cells may lead to receptor–antigen interaction inducing activation, proliferation, and the development of a cytotoxic phenotype." (PMID 39358663, 2024). "EpCAM mediates the adhesion of tumor cells to its primary site." (PMID 37874534, 2024). "First, we tested if EpCAM was involved in tumor formation in xenograft models." (PMID 39010070, 2024). "Moreover, CD90, CD49, CD44, CD24, and ALDH, in addition to EpCAM, are a few surface markers reported for the isolation of BCSCs, as they tend to have altered expression levels when compared to those of other bulk tumor cells." (PMID 38920716, 2024). "Furthermore, in a mouse model of prostate cancer, a subpopulation of tumor cells exhibit a hybrid E/M phenotype, indicated by co-expression of epithelial cell adhesion molecule (Epcam) and vimentin." (PMID 39409910, 2024). "Despite the large number of studies reporting good prognosis in patients with high EpCAM expression, the exact mechanisms by which EpCAM supresses tumor progression remain unclear." (PMID 39010070, 2024). "Histological analysis showed that NIRF signals for both Ac2-800CW and Ec4.1-800CW largely overlapped with microscopically identified tumor areas, as well as cytokeratin and EpCAM staining, thereby confirming binding specificity of both tracers and indicating complete tumor penetration." (PMID 37642704, 2024). "In healthy tissue, EpCAM plays a role in the process of morphogenesis, tissue regeneration, and stem cell maintenance, whereas in cancer, its overexpression has been found to promote tumor progression." (PMID 38928484, 2024). "Furthermore, we extended the analysis to include 5 cancer tissues and 3 benign tumor tissues, along with their paired plasma-derived EVs, focusing on the expression of EpCAM, CD51, and CD49b." (PMID 39479442, 2024). "Therefore, the isolation of EpCAM + CTCs and EpCAM- CTCs is a new strategy to study the heterogeneity of tumor cells." (PMID 39280341, 2024). "One promising tumor-specific target is the epithelial cell adhesion molecule (EpCAM)." (PMID 37642704, 2024). "EpCAM is commonly overexpressed in carcinomas, making it a valuable tumor marker." (PMID 39479442, 2024).
tumor (continued). "In accordance with MRI and CT scan encouraging findings, the tendency of targeted nanocarriers to highly accumulate in the tumor, with less intensity in other organs even at 18 h post-injection, confirmed the active targeting through EpCAM aptamer mediated drug delivery mechanism." (PMID 38561432, 2024). "The dissociated primary tumor cells contained 40-60% EpCAM+ cells consistent with previous reports." (PMID 39963656, 2024). "EpCAM has been shown to contribute to tumor growth and progression through several mechanisms." (PMID 39513807, 2024). "Furthermore, the combination therapy significant enhanced the phosphorylation of TBK1 in EpCam+ tumor cells." (PMID 39023171, 2024). "Two aptamers targeting tumor biomarker EpCAM and PD-L1 are utilized." (PMID 38726017, 2024). "We observed heterogeneous cells within the LCAs, including the EpCAM+ tumor cells, α-SMA+ CAFs and CD45+/CD3+ immune cells, which indicated that LCAs could recapitulate a certain tumor microenvironment of the parental tumors." (PMID 38643164, 2024). "Employing a unified approach, specifically flow cytometry, might enable a more precise comparison of EpCAM expression levels between CTCs and primary tumor cells." (PMID 39456890, 2024). "For therapeutic resistance, the mechanism by which EpCAM promotes tumor cell stemness may contribute to the development of resistance to conventional cancer therapies." (PMID 38791091, 2024). "EPCAM-GFP+ BM-derived cells, that accounted for 21.2 ± 5.1% of the total cell population in tumors, had the highest expression of Thbs1 and Vcan compared to that in EPCAM+ tumor epithelium or EPCAM-GFP- residential stromal cells and also compared to that in MTO or MC38 cells." (PMID 37749092, 2023). "Non-tumour margins of resection tissues showed less EpCAM positivity in 24% (6/25) of histospots." (PMID 37533952, 2023). "EPCAM− tumour cells were also resistant to the anti-microtubule paclitaxel, the DNA intercalant and topoisomerase II inhibitor doxorubicin and ionizing radiation, although these treatments were less efficient in inducing cell death in EPCAM+ tumour cells." (PMID 36949199, 2023). "Tumour extent within the gut wall was equal (50% each) for early and late pT stages among EpCAM overexpressing tumours but two-thirds (8/12) of cases expressing E-cadherin had later pT stage paradoxically, while distant metastasis was negligible among tumours bearing both markers." (PMID 37533952, 2023). "Therefore, the observed EpCAM+Vim+CD24+ cells in our tumour specimens are highly likely to be a tumour cell population." (PMID 37975646, 2023). "This was expected as oncogene-enriched subtype tumours exhibited more aggressive tumour growth and had an increased expression of gene mutations involved in cell proliferation (ERBB2, SLC44A4, EPCAM, CLDN3, and CLDN4), cell differentiation (ELF3 and GPX2), and mucin production (KRT20)." (PMID 36723696, 2023). "Indeed, use of EpCAM as a tumour lineage marker is specifically intended to exclude staining for stromal constituents." (PMID 37975646, 2023). "Another population of β4+ tumor cells with the EpCam+panCK+N-cadherin-E-cadherin+ phenotype prevailed in patients with liver metastases (40.87 (5.01; 76.92), p = 0.0018) and in patients without metastases (26.17 (0; 88.71)%, p = 0.0019) compared with patients with lung metastases (5.42 (0–8.08)%)." (PMID 36769251, 2023). "Also, the actual tumor specificity of EpCAM is assessed by comparison to corresponding healthy tissue." (PMID 37154925, 2023). "Finally, as a side finding of our flow cytometry strategy, we observed a significant reduction in EpCam expression on tumor cells." (PMID 37370706, 2023). "Since EpCAM high-expressing and low-expressing CTCs display similar genomic tumour cell clones, we hypothesise that both CTC subgroups will be of equal predictive value regarding genomic parameters." (PMID 36823365, 2023).
tumor (continued). "Additionally, the EpCAM molecule itself is used as a descriptive therapeutic target in urothelial cancer (UC), while data on its actual tumor specificity remain limited." (PMID 37154925, 2023). "Enrichment of EpCAM+Vim+CD24+ cells in the stroma surrounding metastatic tumours." (PMID 37975646, 2023). "EpCAM+ cells grew much larger tumor spheroids in soft fibrin and more colonies in soft agar than did EpCAM− cells and control cells, while EpCAM− cells generated the smallest spheroids and the least number of colonies, suggesting the high self-renewal of EpCAM+ cells." (PMID 37746658, 2023). "Additionally, it only selects CTCs that express EpCAM, missing other CTC phenotypes such as mesenchymal and stem cell-like tumor cells that express EpCAM at low or zero levels." (PMID 37547763, 2023). "In addition, we investigate the potential correlation between EpCAM expression levels and clinicopathological parameters such as tumor grade, perineural invasion and lymphatic infiltration, distant metastasis, and patient survival." (PMID 37627911, 2023). "However, the distribution of EpCAM in normal epithelia has raised some concerns for off-tumor immunopathology, particularly regarding adverse pulmonary effects." (PMID 36900412, 2023). "Catumaxomab is a trivalent antibody that crosslinks CD3+ T cells with epithelial cell adhesion molecule (EpCAM) expressing tumours in the presence of FcR-bearing myeloid antigen presenting cells, which primes cellular and humoral responses against tumour antigens." (PMID 37580610, 2023). "As expected, RT‐qPCR analysis of the EPCAM+ cells removed from the tumour cell suspension prior to CyTOF analysis confirmed that expression of both TAZ mRNA and the TAZ target CTGF was strongly reduced in the TAZ‐KO cancer cells, relative to the TAZ‐WT cancer cells." (PMID 37716913, 2023). "Higher activation of CDKs, including CDK1 and CDK4, was observed in EPCAM− tumour cells compared with in EPCAM+ and Rhoj-KO EPCAM− cells after chemotherapy suggesting that RHOJ enables EMT tumour cells to progress in the cell cycle and continue DNA synthesis after chemotherapy." (PMID 36949199, 2023). "EpCAM can be found in disseminated tumor cells, circulating tumor cells (CTC) and EVs." (PMID 37375854, 2023). "However, 24 h after cisplatin/5FU administration, the percentage of cells in S phase was strongly reduced in EPCAM+ and Rhoj-KO tumour cells, whereas EPCAM− tumour cells continued to synthesize DNA, as revealed by BrdU incorporation." (PMID 36949199, 2023). "The EpCAM-aptamer coupled siRNA-NPs successfully targeted EpCAM tumor cells, delivered siRNA, silenced the target gene, and repressed cell proliferation more than the scrambled aptamer loaded nano-construct, signifying its efficient targeting ability to EpCAM receptor." (PMID 37149607, 2023). "To conclude, we demonstrate the potential of modular engineered proteins to kill tumor cells highly selectively by simultaneously exploiting EpCAM as a tumor-specific cell surface molecule as well as Ras as an intracellular oncotarget in a 3D system mimicking the natural tumor microenvironment." (PMID 37485031, 2023). "Additionally, utilizing the Copykat algorithm, we identified aneuploid cells that shared similarities with the cell subsets defined by the tumor marker gene “EPCAM,” all of which originated from epithelial cells." (PMID 37608794, 2023). "EpCAM was expressed in 57% of all tumor samples, but only 3% exhibited a homogenous pattern." (PMID 36835265, 2023). "EpCAM is a type I transmembrane protein primarily considered an adhesion molecule; however, studies have shown diverse biological functions, including regulation of cell proliferation and a biomarker of cancer stem cells and circulating tumor cells." (PMID 37895932, 2023). "Moreover, Immunohistochemistry revealed that the human chorionic gonadotropin, cytokeratin 7, and EpCAM expression levels were similar to those in the primary tumour." (PMID 37957624, 2023).
tumor (continued). "EpCAM is another marker highly expressed in tumor cells, including CSCs." (PMID 36900399, 2023). "In addition to its role as an adhesion molecule, EpCAM can function as a signaling molecule and promote or suppress tumor progression, depending on the cancer context." (PMID 37192201, 2023). "Meanwhile, in vivo limiting dilution assay (LDA) performed by xenograft experiment using a series of cell amounts as indicated revealed that YY2 overexpression decreased liver CSC frequency by > 10‐fold, as well as the expression of CSC markers CD44 and EpCAM in the xenografted tumor lesions." (PMID 37300334, 2023). "For example, epithelial cell adhesion molecule (EpCAM) is a transmembrane glycoprotein closely related to cancer metastasis, and the recognition of CTCs usually depends on the presence of EpCAM on the tumor cell membrane." (PMID 37811123, 2023). "Notably, the only responders to the immunotherapy-alone condition (patient 5 and patient 6) correlated with an increased percentage of total CD3+ T cell populations and PD-L1 expression in EPCAM+ circulating tumor cells." (PMID 37627156, 2023). "In the non-tumour cells, only 0.8% (29/3687) were EpCAM+Vim+CD24+." (PMID 37975646, 2023). "Furthermore, EpCAM-gated tumor cells from regressing tumors showed increased HLA-II expression compared to progressing tumors (21% vs. 2% respectively, p = 0.03)." (PMID 37185301, 2023). "EpCAM fragment patterns indicate cancer-specific changes and could be involved in its complex tumor-biological role." (PMID 37154925, 2023). "We also showed that the method could be combined with the immunocapture of target‐specific EVs on gold disk arrays to measure miR‐21‐5p for EpCAM‐positive, tumor‐derived EVs." (PMID 37340600, 2023). "In a xenograft model, a possible profile of brain metastasis marker HER2 + /EGFR + /Heparanase (HPSE) + /Notch1 + in Epithelial Cell Adhesion Molecule (EpCAM)-circulating tumor cells (CTCs) was found to be highly invasive and able to spread to the brain and lungs." (PMID 37386445, 2023). "Tumor cells were identified as EpCam+ cells by flow cytometry approach." (PMID 37370706, 2023). "However, data on the tumor specificity of EpCAM in UC and cancer in general remain sparse and are based on immunohistochemistry." (PMID 37154925, 2023). "Furthermore, innate-like γ∂-T cells can target and kill HBL tumor cells either with the aid of an EpCAM-targeted antibody or by combination therapy with bispecific EpCAM/CD3 antibody and histone deacetylase inhibition." (PMID 37426669, 2023). "The authors also demonstrate multiplexed protein‐miRNA analysis in tumor‐derived EVs by capturing EpCAM‐positive EVs and quantifying miR‐21‐5p‐positive ones in the subpopulation, which show significantly higher counts in the plasma of cancer patients than healthy controls." (PMID 37340600, 2023). "To identify tumor-derived gene markers expressed by cancerous cells from each BC molecular subtype, we initially filtered the single-cell gene expression data and restricted the analysis to epithelial cells (EPCAM+CD45−CD8A−CD4−CD19−CD3E−)." (PMID 37190091, 2023). "Next, we compared the ‘epithelial’ glandular YFP + EpCAM+ and solid YFP + EpCAM- organoid sublines, which showed increased EpCAM expression in the primary tumor glandular organoids and increased vimentin expression in the solid organoids, consistent with their partial EMT phenotypes." (PMID 36828915, 2023). "The TROP2/EpCAM ratio was largely unrelated to tumor phenotype." (PMID 38282671, 2023). "Due to the technical limitations of the positive immunoselection-based methods the development of a protocol that can obtain the possible CTCs without depending on tumor-associated cell surface antigens, such as EpCAM or CKs, is crucial." (PMID 38001632, 2023). "However, some reports have suggested that the cytoplasmic distribution of EpCAM varies according to tumor type and histologic differentiation of the carcinoma." (PMID 37627911, 2023).
tumor (continued). "Furthermore, similar to clinical trial results, responses to ICB in PDOTS tend to be low and positively correlated with the frequency of CD3+ immune cells and EPCAM+/PD-L1+ tumor cells." (PMID 37627156, 2023). "EpCAM has long been utilized to detect circulating epithelial tumor cells and their derived sEVs." (PMID 38129848, 2023). "Also, relative dominance of EpCAM over EpEX was observed in all tumor stages compared to healthy tissue." (PMID 37154925, 2023). "Notably, normal and tumor cells marked by ALDH+/CD49f+/EpCAM+ exhibited different clustering compared to unselected normal and tumor cells." (PMID 37830602, 2023). "The highly variable amount of EpCAM+ cells found in patient blood was expected, since even in metastatic patients circulating tumor cells can be quite rare and heterogeneous in terms of EpCAM expression (which can be gained and lost, especially during HCC cancer progression)." (PMID 37373781, 2023). "In cancer, the prognostic significance of EpCAM expression is dependent on the tumor type." (PMID 37192201, 2023). "These vectors have demonstrated the ability to recognize EpCAM-positive tumor cells in vitro." (PMID 38082377, 2023). "Immunohistochemical analysis of EpCAM expression in tumor and liver tissue slices showed that EpCAM expression in tumor tissue was positive, which was consistent with the positive expression of luciferase detected only in the tumor slices of the AAV2MEC1 group." (PMID 38082377, 2023). "Furthermore, we observed increased CD31+ endothelial cells, decreased lesions, and increased EPCAM expression in lesions, suggesting an early tumor phenotype." (PMID 38111825, 2023). "Determined by tumor volume and the tumor cell apoptosis (TUNEL+EPCAM+), we found that co-injection of TAMs, NBFs and tumor cells MCF-7 dramatically enhanced the chemoresistance of MCF-7 cells, compared with the mice co-injected with MCF-7 cells and NBFs or MCF-7 cells and TAMs." (PMID 36418470, 2023). "The CD45− population consisted of a large portion of EpCAM+ cells and as epithelial cells are the cell-of-origin for this type of tumor, we sorted freshly isolated pHNSCC samples for EpCAM as described by others and expanded the samples in an epithelial cell-specific medium." (PMID 37370779, 2023). "The relationship of EpCAM expression with tumor phenotype was highly similar as seen for TROP2." (PMID 38282671, 2023). "EpCAM-bearing tumours are also more likely to attract TALs whose role needs to be ascertained." (PMID 37533952, 2023). "Two of these tumor cell populations expressed EpCAM, FOLR1, and CD24 simultaneously." (PMID 37894472, 2023). "Several treatment strategies targeting EpCAM have shown benefits for different tumor types." (PMID 36900394, 2023). "EpCAM-positive OC cells exhibit higher tumour-initiating potential than EpCAM-negative cells." (PMID 38201468, 2023). "Additionally, immunohistochemical staining showed that the expression of hCG, CK7, and EpCAM was retained in all passages of PDX tumours." (PMID 37957624, 2023). "EpCAM has also been used as epithelial marker to detect circulating tumor and cancer stem cells." (PMID 37154925, 2023). "There is also evidence that EpCAM can affect tumor recurrence." (PMID 36674932, 2023). "It is of note that similar observations were recorded by brightfield immunohistochemistry in analyses of partially overlapping sets of pTa tumors in separate studies determining the expression of TROP2 and EpCAM in >10,000 tumors from up to 150 different tumor entities." (PMID 38282671, 2023). "To determine whether the cell cycle is differentially regulated in EPCAM+, EPCAM− and EPCAM−Rhoj-KD tumour cells in response to chemotherapy, we assessed DNA content and BrdU incorporation using BrdU/7AAD FACS analysis." (PMID 36949199, 2023). "Therefore, antibodies targeting EpCAM have been established many years ago to capture CTCs and proven to capture tumour cells from the blood whose numbers have a high prognostic value." (PMID 36823365, 2023).